RN7SL362P (RNA, 7SL, cytoplasmic 362, pseudogene)
Gene: Miscellaneous RNA gene on chromosome 18 (13,715,102 to 13,715,368, reverse strand). Ensembl gene ENSG00000242707.
Homologues: Orthologues: chimpanzee Metazoa_SRP (99% identical), macaque Metazoa_SRP (94% identical). Paralogues in human: RN7SL2 (85% identical), RN7SL1 (84% identical), RN7SL126P (84% identical), RN7SL3 (83% identical), RN7SL326P (82% identical), RN7SL145P (82% identical), RN7SL45P (82% identical), RN7SL300P (81% identical), RN7SL441P (81% identical), RN7SL597P (81% identical), RN7SL230P (81% identical), RN7SL679P (81% identical), and 708 more.